IDH2 (isocitrate dehydrogenase (NADP(+)) 2)
Diseases named in the same sentence as IDH2 in open-access papers (continued):
Sharing a sentence is not in itself a finding about the gene and the disease.
glioma (continued). "Mutations in the cytoplasmic IDH1 and in the mitochondrial IDH2 mutations occur in various human cancers, including gliomas, glioblastoma, and acute myelogenous leukemias (AMLs)." (PMID 28352611, 2017). "The effects of IDH1 and IDH2 mutations on α-ketoglutarate flux and accumulation of 2-hydroxyglutarate leading to altered intracellular signaling in glioma cells, have been extensively reviewed elsewhere." (PMID 28491867, 2017). "Isocitrate dehydrogenase 1 (IDH1) and IDH2 genes are frequently mutated in low-grade gliomas, denovo acute myeloid leukemias in adult and in the subsets of chondrosarcomas and lymphomas." (PMID 27377127, 2016). "Mutations in the metabolic proteins IDH1 and IDH2 are associated with gliomas, acute myeloid leukemias, chondrosarcomas, intrahepatic cholangiocarcinomas, lymphomas, melanomas and colon, thyroid and prostate cancers." (PMID 26971564, 2016). "To investigate the different clinical and molecular characterization between IDH1 mutant and IDH2 mutant gliomas, we studied 811 patients with IDH1 mutations, IDH2 mutations and IDH1/2 wild-type." (PMID 27245697, 2016). "Mutations in the IDH1 and IDH2 genes have been found in patients with gliomas and were initially identified in low-grade gliomas and secondary glioblastomas." (PMID 27245697, 2016). "Most notably, cytosolic IDH1 is mutated in 70–90% of low-grade gliomas and upgraded glioblastomas, and mitochondrial IDH2 is mutated in ~20% of acute myeloid leukemia cases." (PMID 27014635, 2016). "The main prognostic variable for patients with glial tumors is the mutational status of IDH1 or IDH2." (PMID 27923049, 2016). "Mutations in IDH1 and IDH2 regard the majority of low-grade gliomas in adults, defining a subtype associated with a better prognosis." (PMID 27338365, 2016). "In recent years, mutations in isocitrate dehydrogenase 1 (IDH1) and IDH2 have been shown to characterize low-grade glioma and secondary glioblastomas." (PMID 26911558, 2016). "CIMP (CpG island methylator phenotype) is now recognized in many different tumor types and in the case of glioma is caused by mutations in IDH1/IDH2." (PMID 26646321, 2016). "TET2 mutations in various myeloid cancer, or mutations of IDH1 and IDH2 in low-grade gliomas, which can inhibit DNA hydroxymethylation by TET enzymes, have been reported and cause DNA hypermethylation phenotype." (PMID 27829228, 2016). "We compared the mutational landscapes of IDH1 and IDH2 mutant gliomas, their clinical associations, overall survival, and progression-free survival." (PMID 27245697, 2016). "Of particular interest is that all these mutations occur exclusively in the R132 residue of IDH1 or the corresponding R172 residue of IDH2, with the R132H mutation being predominant (>90 %) in these gliomas." (PMID 27316347, 2016). "From these analyses we have provided evidence to implicate BRCA2 p.(Lys3326Ter) as well as IDH2 p.(Arg261His) as determinants of glioma risk." (PMID 26264438, 2016). "IDH1 and IDH2 are mutated in >75% of low grade gliomas and secondary glioblastoma multiforme (GBM), and 20% of AML." (PMID 27548812, 2016). "Mutations in the metabolic enzymes IDH1 and IDH2 are frequently found in glioma, cholangiocarcinoma, T-cell lymphomas, thyroid cancer, chondrosarcoma, and AML." (PMID 27806325, 2016). "Subsequently, another study showed the presence of mutated IDH1 (R132) and IDH2 (R172) genes in a majority of grade II or III gliomas and in secondary glioblastomas." (PMID 26668680, 2016). "These interesting findings should be verified in more cases before accepting them as general characteristics of IDH2-mutated gliomas." (PMID 27245697, 2016). "To characterize the molecular features of IDH2 mutant gliomas, we analyzed associations between IDH2 mutations and other mutational events." (PMID 27245697, 2016).
glioma (continued). "In conclusion, our results describe the clinical and biological characteristics of IDH1 and IDH2 mutations in gliomas." (PMID 27245697, 2016). "Combined IDH1 and IDH2 mutations were found in 14.6 % (30/205) of pGBM, 58.6 % (17/29) of sGBM and 72.6 % (419/577) of low grade gliomas." (PMID 27245697, 2016). "Mutations in IDH1 and/or IDH2 have been identified in gliomas as well as in hematological malignancies." (PMID 25823555, 2015). "The introduction of an IDH2 R172K mutation, the main IDH2 mutation in gliomas, into C3H10T1/2 was previously shown to reduce the expression of the COL2A1 gene and gave rise to poorly differentiated sarcomas in xenograft models." (PMID 26161668, 2015). "Somatic heterozygous IDH1 or IDH2 mutations have frequently been detected in glioma/glioblastomas by genome wide mutation searches." (PMID 26161668, 2015). "The strongest prognostic factor for all glioma histologies is mutation in one of the isocitrate dehydrogenase genes (IDH1 or IDH2), and mutation of these genes is seen at higher frequencies in lower grade gliomas and secondary GBMs." (PMID 26091668, 2015). "Somatic mutations in IDH1 and IDH2 have been demonstrated in many human cancers including low grade glioma, glioblastoma, cholangiocarcinoma, chondrosarcoma, and acute myeloid leukemia as recently summarized." (PMID 26097881, 2015). "An integrated genomic analysis found recurrent heterozygous mutations in the active site of IDH1 and IDH2 isoforms in high proportion of low-grade glioma and acute myeloid leukemia (AML) patients." (PMID 26130389, 2015). "Mutations in isocitrate dehydrogenase 1 (IDH1) and IDH2 are found in a subset of benign and malignant cartilage tumors, gliomas and leukaemias." (PMID 25895133, 2015). "Mutations in IDH1 or IDH2 are frequently observed in human cancers, particularly with high frequency in secondary glioma, acute myeloid leukemia, and chondrosarcoma." (PMID 25825982, 2015). "We have investigated the mutational status of IDH1 and IDH2 in a cohort of 1305 glioma patients and correlated it with the genomic profile and the outcome." (PMID 24877111, 2014). "Aberrations in both IDH1 and IDH2 genes have been associated with better prognosis in glioma patients of various grades." (PMID 24868540, 2014). "Mutations in isocitrate dehydrogenase genes IDH1 or IDH2 are frequent in glioma, and IDH mutation status is a strong diagnostic and prognostic marker." (PMID 24889502, 2014). "In this large series, we investigated the place of IDH1/IDH2 mutation in gliomas, in particular in different genotypes and phenotypes." (PMID 24877111, 2014). "The concept of oncometabolite was established by the studies that mutations of isocitrate dehydrogenase 1 (IDH1) and IDH2 generate a novel metabolite 2-hydroxyglutarate (2-HG) that exhibits oncogenic activity in acute myeloid leukemia and glioma." (PMID 25060643, 2014). "Mutations have been found not only in IDH1 and IDH2, predominantly in gliomas, but also in leukemia samples and very rarely in other cancers." (PMID 24868540, 2014). "Downregulated isoforms of IDH3 were also noted, and IDH1 and IDH2 mutations have recently been reported in gliomas." (PMID 24728830, 2014). "For example, IDH1 and IDH2 mutations are associated with much better glioma patient prognosis, and the BRAF mutation was associated with more favorable acral lentiginous melanoma prognosis." (PMID 25332145, 2014). "Curiously, a separate group of gliomas harbour mutations in the IDH1 homologue IDH2 at the analogous residue (R172)." (PMID 25147764, 2014). "The presence of IDH2 mutation was investigated in a cohort of 980 gliomas (379 grade II, 289 grade III, 312 grade IV)." (PMID 24877111, 2014). "For example, IDH1 and IDH2 mutations are associated with better glioma patient prognosis, and Braf mutations are associated with better prognosis in acral lentiginous melanoma." (PMID 25332145, 2014).
glioma (continued). "In grades II and III gliomas, IDH2 mutations were overrepresented in oligodendrogliomas (22 IDH2 mutations out of 330 IDH mutated tumors; 6.7%), compared to astrocytomas (1/60; 1.7%) and mixed gliomas (6/176; 3.4%) (P = 0.049)." (PMID 24877111, 2014). "When with the development of sequencing technologies, researchers found mutations in IDH1, IDH2 (isocitrate dehydrogenase) in medium-grade glioma and acute leukemia." (PMID 25232952, 2014). "Subsequent studies have shown that IDH2 mutations are also enriched in WHO grade II/III gliomas, albeit less frequently, and that IDH1/2 mutations occur in a mutually exclusive manner." (PMID 24622842, 2014). "To define the co-occurrence of IDH1/2 mutations and the presence of TERT promoter mutations, we determined the status of IDH1 and IDH2 mutations in the same cohort of 473 gliomas and identified mutations in 47.9% (227/473) of tumors." (PMID 24722048, 2014). "In contrast, IDH2 mutations were reported as IDH2-R172K (20/31: 64.5%), IDH2-R172M (6/31: 19.3%), and IDH2-R172W (5/31: 16.2%) in gliomas." (PMID 24403254, 2013). "In this review, we summarize the frequency and role of IDH1 and IDH2 mutations in gliomas and myeloid neoplasms, the latter with an emphasis on AML, and the association of these mutations with clinical, morphologic, cytogenetic, and molecular characteristics." (PMID 23847760, 2013). "In the present study, we investigated the mutation status of IDH1 and IDH2 in 53pairs of primary and recurrent gliomas." (PMID 23840696, 2013). "IDH1/IDH2 mutation was detected in 32 primarytumors, with 25 low- grade gliomas and 6 anaplastic gliomas harboring IDH1 mutation and 1 low- grade glioma harboring IDH2 mutation." (PMID 23840696, 2013). "Somatic mutations of isocitrate dehydrogenase (IDH) 1 and IDH2 occur in gliomas, acute myeloid leukemia, and cartilaginous tumors." (PMID 24403254, 2013). "Isocitrate dehydrogenase isoforms 1 and 2 (IDH1 and IDH2) mutations have received considerable attention since the discovery of their relation with human gliomas." (PMID 23894344, 2013). "IDH1 and IDH2 mutations are well known in gliomas, but are notoriously difficult to grow in culture." (PMID 22928481, 2012). "The abnormal expression of IDH2 has been reported in several types of cancer, and mutations in IDH2 have been identified in gliomas and acute myelogenous leukemia." (PMID 23226729, 2012). "Conversely, genomewide mutation analyses and high-throughput deep sequencing revealed the presence of mutations in either IDH1 or its mitochondrial counterpart IDH2 in 70% of grade II-III gliomas and secondary glioblastomas." (PMID 22888353, 2012). "Recent studies also proved that IDH1 or IDH2 mutations predicted longer survival and response to temozolomide in low-grade gliomas." (PMID 22291938, 2012). "This demonstrates for the first time to our knowledge that gliomas with IDH2 R172 mutations can have elevated 2HG, that any cancer with IDH1 R132L or IDH2 R172M have elevated 2HG, and that 2HG in cancer tissues is specific for (R)-2-hydroxyglutarate." (PMID 21326614, 2011). "Both IDH1 and IDH2 mutations are more frequent in grade II-III gliomas and secondary glioblastoma (70–75%) than in primary glioblastoma (5%), are present at higher frequencies in younger patients, and are associated with a relatively favourable prognosis." (PMID 21625441, 2011). "Mutations in IDH1 and IDH2 are essential for glioma classification and prognosis." (PMID 41154393, 2025). "Moreover, mutations in IDH1 and IDH2, recurrently observed in gliomas and acute myeloid leukemias, lead to the neomorphic production of 2-hydroxyglutarate (2HG), a competitive inhibitor of αKG-dependent dioxygenases." (PMID 41411367, 2025). "Mutations in the IDH1 and IDH2 genes are present in glioma at varying rates." (PMID 40564017, 2025).
glioma (continued). "Patients with gliomas harbouring IDH1 or IDH2 mutations have been shown to have a decreased risk of thromboembolism, which may be related to a decreased expression of tissue factor, leading to a decrease in coagulation system activation." (PMID 40862818, 2025). "Notably, breast cancer seldom exhibits mutations in IDH1 and IDH2, which are known to drive 2HG accumulation in gliomas and leukemia, suggesting alternative mechanisms are responsible for the elevated 2HG levels observed in breast cancer." (PMID 39910592, 2025). "The IDH2 R172S mutation found in the present case is extremely rare in gliomas." (PMID 40697380, 2025). "Notably, mutations in IDH1 and IDH2 are well-characterized in lower-grade gliomas and secondary GBM, leading to the production of the oncometabolite 2-hydroxyglutarate (2-HG), which contributes to epigenetic dysregulation and tumorigenesis." (PMID 40282990, 2025). "IDH1 mutations occur in gliomas more frequently than IDH2 mutations." (PMID 40428422, 2025). "In a preliminary study (unpublished) in our laboratory, mutation profiling by Sanger sequencing of hot-spot regions of four glioma-related genes (Idh1, Idh2, Braf, and Egfr) identified point mutations in Egfr gene in 55% (6/11) of the gliomas from chemical-exposed HSD: Sprague Dawley® SD rats." (PMID 38232086, 2024). "Therefore, R172K is expected to affect enzyme activity; the IDH2 variants are less common, with R172K observed in 3% of glioma patients, and detection of the R172K variant has implications for glioma diagnosis, prognosis, and potential treatment." (PMID 39457600, 2024). "Notably, mutations in the IDH1 and IDH2 genes are recognized for their role in lower-grade gliomas and secondary glioblastomas, offering prognostic and therapeutic implications." (PMID 39397895, 2024). "Interestingly, the absence or rarity of mutations in IDH1 R132 and IDH2 R172 was also demonstrated in gliomas from dogs, another important model system with significant human relevance." (PMID 38232086, 2024). "IDH2 ANT relationship suggests functional redundancy with IDH1 mutations in glioma pathogenesis." (PMID 39160568, 2024). "IDH1 and IDH2 mutational status is a critical biomarker in the evaluation of glioma." (PMID 38796421, 2024). "Much less commonly, in less than 1% of IDH mutant gliomas, is IDH2 (mutation at R172)." (PMID 39767640, 2024). "For instance, the reduction of TET2 enzyme levels by promoter methylation in absence of TET2 mutation was reported recently in low-grade diffuse astrocytomas, suggesting that this represents an additional pathomechanism in IDH1- and IDH2-mutated low-grade gliomas." (PMID 39090080, 2024). "Mutations in IDH1 and IDH2 are common in cancers like gliomas and acute myeloid leukemia." (PMID 39765841, 2024). "IDH2 mutations are substantially rare events in gliomas, accounting for 0.3–5.2% of cases." (PMID 39684714, 2024). "Mutations in IDH1 and, less frequently, IDH2 now define a secondary glioblastoma (low-grade gliomas that eventually underwent a malignant transformation), whereas the IDH1 wild-type is considered to be a primary glioblastoma that arose as a higher-grade tumour." (PMID 39767640, 2024). "Polymorphism for IDH2 was selected for its biological importance in the development of gliomas." (PMID 39457600, 2024). "Both of IDHmut gliomas carry a hotspot missense mutation in IDH1 or IDH2." (PMID 37932833, 2023). "Consequently, Ag-881 was tested in a phase III clinical trial (INDIGO) in patients up/equal to 12 years of age and with residual or recurrent grade 2 Glioma who carried an IDH1 R132H/C/G/S/L or IDH2 mutation." (PMID 37397394, 2023). "IDH1 and IDH2 mutations result in the production of reduced alpha-ketoglutarate (α-KG) levels and increased 2-hydroxyglutarate (2-HG), which influence histone and DNA methylation profiles in glioma." (PMID 36984785, 2023).
glioma (continued). "It is of particular interest to note that the pro-tumor role of wild-type IDH2 and its underlying mechanisms are different from the oncogenic function of IDH2 mutations, which are most often observed in certain gliomas and leukemia, such as acute myeloid leukemia (AML)." (PMID 36831011, 2023). "Additionally, methylation in MGMT promoter, deletion in chromosome 1p and 19q, and isocitrate dehydrogenase (IDH) 1 and IDH2 mutations are used for diagnosing or treating patients with glioma." (PMID 37851374, 2023). "GSC stemness is thought to be affected by IDH1 and IDH2 mutations in the glioma." (PMID 37894287, 2023). "Indeed, AG-881 is currently under a phase 1, open-label, dose-escalation and expansion trial for the safety and pharmacokinetic properties to be investigated in both IDH1 and IDH2 mutated gliomas." (PMID 37296846, 2023). "IDH-mutant gliomas are genetically defined by the presence of the IDH1 or IDH2 gene mutation." (PMID 37174088, 2023). "IDH1/IDH2 mutations are associated with a favorable prognosis in patients with glioma and may confer a survival benefit for patients treated with radiation or alkylating chemotherapy [13, NCCN.org]." (PMID 37483495, 2023). "Low-grade and secondary high-grade gliomas frequently contain mutations in the IDH1 or IDH2 metabolic enzymes that are hypothesized to drive tumorigenesis by inhibiting many of the chromatin-regulating enzymes that regulate DNA structure." (PMID 37528157, 2023). "Moreover, mutations of IDH1 and IDH2 have been detected in many types of cancer, including gliomas and myeloid malignant tumors; furthermore, these enzymes have been confirmed to be closely related to the occurrence and development of cancer." (PMID 38139250, 2023). "Isocitrate dehydrogenase (IDH) 1 and IDH2 mutations (IDH1/2mt) are frequent in glioma." (PMID 36968138, 2023). "The results showed that IDH1 mutation was dominant in glioma compared with IDH2." (PMID 35982398, 2022). "In addition, IDH2 active‐site mutations mainly occurred at the R172 codon site in glioma, whereas the R140 codon was the most common mutation site in NSCLC and AML." (PMID 35526267, 2022). "IDH1 and IDH2 mutations were subsequently found in patients with WHO grade II/III gliomas." (PMID 36290819, 2022). "In addition, mutations in genes encoding isocitrate dehydrogenases 1 and 2 (IDH1 and IDH2) are also found in low grade gliomas (grades II and III) and secondary GBMs (GBM, IDH-mutant)." (PMID 35455961, 2022). "These metaoboliets in turn accumulate in IDH1 or IDH2 mutated gliomas to millimolar concentrations." (PMID 35382567, 2022). "Various studies have reported spontaneous mutations in the NADP+-dependent IDH1 gene in glioma along with mutation in the IDH2 gene which is located on 15q26.1 chromosomal position with a frequent mutation at R172K (sometimes also at R172K, R172W, and R172M) of R172." (PMID 35873570, 2022). "Our analysis shows frequent mutations of IDH1 and IDH2 in the TCGA LGG (lower grade glioma) cohort and frequent amplifications of IDH1 in LIHC (liver hepatocellular carcinoma), as well as less frequent mutations and amplifications of IDH1 in CHOL, GBM, PRAD and SKCM." (PMID 35975235, 2022). "IDH2 mutations have been associated with improved prognosis in gliomas." (PMID 36304962, 2022). "Although IDH1 and IDH2 mutations are associated with better OS in glioma patients, it is controversial whether OS has a good correlation with chondrosarcoma patients." (PMID 33981605, 2021). "Mutations in IDH1 or IDH2 are known to be drivers of tumorigenesis in both gliomas and AML." (PMID 34356864, 2021). "Therefore, we mined the human cancer data derived from 37 different types of cancers, finding a high rate of IDH1 and IDH2 mutations in a tissue-specific manner mainly in gliomas suggesting a role for these genes in carcinogenesis." (PMID 35996504, 2021). "IDH2 mutations are less common, but also present in the glioma." (PMID 34088969, 2021).